CASR (calcium sensing receptor)
Diseases named in the same sentence as CASR in open-access papers (continued):
Sharing a sentence is not in itself a finding about the gene and the disease.
colon carcinoma (continued). "In colon carcinoma, CaSR is downregulated during tumorogenesis, leading to growth suppressive effects of high Ca2+." (PMID 32252342, 2020). "CaSR expressions were detected in the mouse jejunal mucosa and human colon cancer cells SW480 and SW620." (PMID 31960592, 2020). "In other cells—differentiated human colon carcinoma cells—upregulation of the CaSR occurred when the Ca2+ concentration of the culture medium was increased from very low to normal." (PMID 27679579, 2016). "In colon cancer cell lines other miRNAs, miR-21, miR-145, and miR-135a, are inversely correlated with CaSR expression." (PMID 27679579, 2016). "Colon cancer cells transfected with CaSR express lower levels of thymidylate synthase (TS), an enzyme involved in de novo DNA synthesis which is the target of the main colon cancer drug 5-fluoro uracil (5-FU)." (PMID 27803671, 2016). "Both VDREs are often methylated in colon cancer, and the level of silencing of the CaSR varies depending on the level of DNA methylation and of histone acetylation at distinct residues." (PMID 27803671, 2016). "Increasing CaSR expression in colon cancer cell lines led to reduced nuclear translocation of ß-catenin and to higher E-cadherin protein levels." (PMID 27803671, 2016). "We were able to show that transfection of the HT29 colon cancer cell line with the functional CaSR prevented epithelial-to-mesenchymal transition and upregulation of SNAIL1." (PMID 27803671, 2016). "In a colon cancer cell line the effect of 1,25D3 on Cdkn1a was abolished by knocking down the CaSR by CaSR-shRNA transfection." (PMID 27803671, 2016). "In colon cancer cells CaSR activation increased expression of the low density lipoprotein receptor-related protein 6 (Lpr6)." (PMID 27803671, 2016). "1,25D3 was also able to upregulate DKK-1 expression in colon cancer cell lines similar to the effect of CaSR in myofibroblasts." (PMID 27803671, 2016). "In vitro, stable expression of the CaSR (HT29CaSR) gave a more epithelial-like morphology to HT29 colon cancer cells with increased levels of E-Cadherin compared with control cells (HT29EMP)." (PMID 25879211, 2015). "These cell lines have low endogenous CaSR expression compared with more differentiated colon cancer cells having a more epithelial phenotype (e.g. Caco-2 cells)." (PMID 25879211, 2015). "CaSR-null cells, which represent a subpopulation of colon cancer cells, indeed show an enhanced malignant phenotype with increased migration potential and enhanced expression of EMT markers." (PMID 25879211, 2015). "Our data demonstrates that reintroduction of the CaSR prevents the development of a highly malignant, stem cell-like phenotype in colon cancer cells." (PMID 25879211, 2015). "In contrast to these results, in colon carcinoma cells and neuroblastoma cells, calcium and activation of the CaSR have been shown to inhibit proliferation and induce apoptosis, indicating CaSR as a tumor suppressor." (PMID 24576174, 2014). "Treatments with 5-aza-2′-deoxycytidine (DAC), a DNA methyltransferase inhibitor and/or with two different histone deacetylase inhibitors, trichostatin A (TSA) or suberoylanilide hydroxamic acid (SAHA) restored the expression of CaSR in colon cancer cells." (PMID 24691920, 2014). "In tumor samples from colon cancer patients we found higher percentages of methylated CpG sites in the CaSR promoter 2 when compared with samples of apparently normal adjacent mucosa." (PMID 24691920, 2014). "In conclusion, our results demonstrate for the first time that in colon cancer cells not only 1,25D3, but also the proinflammatory cytokines TNFα and IL-6 were able to induce the expression of CaSR." (PMID 24176760, 2014). "We determined mRNA expression of the CaSR in five colon tumor cell lines Coga1A, Coga13, Caco2/AQ, HT29, and LT97 using real time qRT-PCR." (PMID 24691920, 2014).
colon carcinoma (continued). "This suggests that methylation of the CaSR promoter is an early phenomenon in the process leading to colon cancer and can affect the apparently normal adjacent mucosa." (PMID 24691920, 2014). "The CaSR on human colon carcinoma cells has high sequence homology with the parathyroid CaSR, and is expressed as long as the cancer cells retain a certain degree of differentiation." (PMID 23340319, 2013). "In the present study it has been shown that TDH, a well-known traditional virulent factor inhibits proliferation of human colon carcinoma cells through the involvement of CaSR in its mechanism." (PMID 21625458, 2011). "Recent studies suggest that the extracellular calcium-sensing receptor (CaSR) is involved in the regulation of colon carcinoma cell growth and differentiation." (PMID 16278666, 2005). "The CaSR promoter has two distinct Ca2+-responsive sites and exposure of colon carcinoma cells to extracellular Ca2+ upregulates CaSR expression." (PMID 16278666, 2005). "The CaSR is expressed in a number of human colon carcinoma cell lines derived from moderately-differentiated tumours." (PMID 16278666, 2005). "To investigate whether the pro-inflammatory effects of calcimimetics in the colon are indeed mediated via the CaSR, we used the colon cancer cell line HT29 transfected either with the CaSR (HT-29CaSR-GFP) or with the empty vector (HT29GFP)." (PMID 34576291, 2021). "A recent report suggested that CaSR suppresses the malignant behavior of colonic cancer cells by regulating the Wnt signaling pathway including GSK3β and Cyclin D1, which was proved to be vitally important in the development and the growth of LUAD in previous studies, including ours." (PMID 32671062, 2020). "To address whether the CaSR, a tumor suppressor in the colon, was involved in regulating the DNA replication machinery, we transfected the HT29 colon cancer cells, which have very low endogenous CaSR levels, with the full-length CaSR." (PMID 28161520, 2017). "Reduced levels of CaSR and reduced responsiveness to active vitamin D in parathyroid neoplasia and colon carcinoma may blunt the “tumor suppressor” activity of the CaSR." (PMID 27679579, 2016). "In two colon cancer cell lines expressing undetectable levels of CaSR 1.4 mM Ca2+ or 1 μM 1,25D3 were able to reduce CaSR promoter methylation and thus contribute to the upregulation of CaSR expression." (PMID 27803671, 2016). "We demonstrate that the CaSR suppresses EMT and the stem cell-like phenotype both, in vivo in the colon of mice and in vitro, in colon cancer cells, providing rationale for developing pharmacological agents to modulate CaSR sensitivity in colorectal cancer to prevent tumor progression." (PMID 25879211, 2015). "Therefore, in the current study we investigated the impact of 1,25D3, tumor necrosis factor alpha (TNFα), and interleukin (IL)-6 on CaSR expression in a differentiated (Caco2/AQ) and in a moderately differentiated (Coga1A) colon cancer cell line." (PMID 24176760, 2014). "To investigate whether inhibition of DNA methylation with the DNMT1 inhibitor DAC would increase CaSR expression, we initially treated all five colon tumor cell lines: Coga1A, Coga13, Caco2/AQ, HT29, and LT97 with 1 μM DAC for 72 hr (data not shown)." (PMID 24691920, 2014). "The sequence of events downstream of CaSR activation that actually link CaSR to cell cycle control in colon carcinoma cells starts with inhibition of phospholipase A2 activity, which would reduce the amount of arachidonic acid available for the synthesis of proliferation-stimulating prostaglandins." (PMID 23340319, 2013). "Therefore TDH can downregulate colonic carcinoma cell proliferation and involves CaSR in its mechanism of action." (PMID 21625458, 2011).
colon carcinoma (continued). "Studies of colon carcinomas and neuroblastomas have emphasized the importance of epigenetic changes—promoter methylation of the GC-rich P2 promoter, histone acetylation—as well as involvement of microRNAs in bringing about CASR gene silencing and reduced CaSR expression." (PMID 27679579, 2016). "Extracellular Ca2+ and 1,25(OH)2D upregulate CASR transcription and cyclin-dependent kinase inhibitor expression in the colon and Ca2+ and 1,25(OH)2D may exert their chemopreventative actions with respect to colon cancer, in part, through the CaSR." (PMID 27679579, 2016). "Thus, CaSR expression decreases the tumorigenicity of parathyroid and colon cancers." (PMID 27303307, 2016). "There have been a number of studies examining associations of CaSR polymorphisms with variables such as serum calcium concentrations, PTH levels, severity of primary hyperparathyroidism, calcium excretion, renal stones, fractures, bone mineral density, and risk of colon cancer." (PMID 25695075, 2015). "Increasing CaSR levels, either by transfection (HT29CaSR) or by treatment with NPS R-568 reduced the stem-like phenotype in these cells by downregulating expression of pluripotency associated genes, SOX2, Nanog, Oct4, and the colon cancer stem cell marker, CD44." (PMID 25879211, 2015). "Therefore, in the present study, we studied the impact of 1,25D3, TNFα, and IL-6 on transcriptional and translational regulation of CaSR in two colon cancer cell lines with different proliferation and differentiation properties, mimicking different tumor stages." (PMID 24176760, 2014). "The present study provides evidence that MAP kinase signalling and CaSR upregulation are both critically involved as upstream regulators of Ca2+-induced E-cadherin expression (and the subsequent changes in growth and differentiation) in cells derived from human colon cancer." (PMID 16278666, 2005). "As activation of the calcium-sensing receptor (CaSR) induces expression of inflammatory markers in the colon, we assessed the impact of the CaSR on the PGE2 pathway regulation in colon cancer cells and the colon in vitro and in vivo." (PMID 37153788, 2023). "Methods and Results: We treated CaSR-transfected HT29 and Caco-2 colon cancer cell lines with different orthosteric ligands or modulators of the CaSR and measured gene expression and PGE2 levels." (PMID 37153788, 2023). "Overexpression of the CaSR prevented the mesenchymal transition and the acquisition of stem cell-like properties in the HT29 colon cancer cell line reducing the metastatic properties of the cells." (PMID 27803671, 2016). "In vitro 1,25D3 increased CaSR expression in a thyroid C cell line, in the proximal tubule human kidney cells (HKC), and in colon cancer cells." (PMID 27803671, 2016). "All preliminary experiments were conducted in two colon cancer cell lines: HT29 and Caco2-15, stably overexpressing the CaSR (or the empty control vector)." (PMID 25879211, 2015). "Taken together, these data indicate that both CaSR upregulation and MAP kinase signalling are critical intermediates in the control of colon carcinoma cell growth and differentiation." (PMID 16278666, 2005). "Together, these data indicate that CaSR upregulation and MAP kinase signalling are both intermediates in the control of colon carcinoma cell growth and differentiation." (PMID 16278666, 2005). "Activation of the CaSR with positive allosteric CaSR modulators (calcimimetics) enhanced several inflammatory pathways in CaSR-transfected colon cancer cells, while treatment with negative allosteric CaSR modulators (calcilytics) prevented this upregulation." (PMID 39770982, 2024). "In colon cancer cells, CASR activation stimulates secretion of WNT5A in the noncanonical Wnt signaling pathway." (PMID 37377737, 2023). "Mice bearing C26-DCT colon tumors treated with Cinacalcet to reduce hypercalcemia presents an interesting case as the tumor cells do not express the CaSR." (PMID 32117726, 2020).
colon carcinoma (continued). "CaSR expression is weak or absent in colon carcinomas and is inversely correlated with differentiation status." (PMID 27679579, 2016). "CaSR has been reported most highly expressed in well-differentiated regions of colon cancer and nearly lacking in poorly differentiated sites." (PMID 18980667, 2008). "Since the chemopreventive properties of Ca2+ are partially mediated by the CaSR, these effects may be limited in colonic tumors lacking the CaSR." (PMID 25879211, 2015). "The CaSR gene has a large CpG island (CGI) in promoter 2,27,28 therefore, we hypothesized that methylation of this promoter could be a key determinant of CaSR expression and its silencing in colon cancer." (PMID 24691920, 2014).
primary hyperparathyroidism (35 papers, 2009 to 2026). "Gain-of-function CaSR mutations result in autosomal dominant hypocalcemia, whereas loss-of-function CaSR mutations cause severe neonatal primary hyperparathyroidism." (PMID 31719824, 2019). "A meta-analysis was possible for VDR rs1544410 gene polymorphism in patients with ESRD and CaSR rs1801725 gene polymorphism in patients with primary hyperparathyroidism." (PMID 29794776, 2018). "We conducted meta-analyses for calcium-sensing receptor gene (CaSR) rs1801725 polymorphism in patients with primary hyperparathyroidism and vitamin D receptor gene (VDR) rs1544410 polymorphism in patients with end-stage renal disease (ESRD)." (PMID 29794776, 2018). "The molecular basis for the development of the reduced CaSR expression that likely causes the decreased responsiveness of pathological parathyroid glands to Cao2+ in primary hyperparathyroidism is still not fully understood." (PMID 23227372, 2012). "It has been demonstrated that individuals with FHH are heterozygous, and children within these families with severe neonatal primary hyperparathyroidism (NSHPT) are homozygous for CASR mutations." (PMID 22527485, 2012). "In contrast to the clinically benign course of FHH, neonates with de-novo or paternally derived mutations in CaSR may present with neonatal severe primary hyperparathyroidism (NSHPT)." (PMID 35566721, 2022). "In addition, patients with primary hyperparathyroidism have been reported to harbor CaSR gene mutations." (PMID 35095753, 2021). "Thus, children inheriting biallelic loss-of-function CaSR mutations from FHH1 parents can develop neonatal severe primary hyperparathyroidism." (PMID 32150253, 2020). "This hypothesis received further support by a comparison of another CASR gene regulatory SNP and R990G with respect to stone risk in primary hyperparathyroidism." (PMID 27679579, 2016). "Features of patients with isolated primary hyperparathyroidism diagnosed with a GCM2 p.Y394S variant, CASR, and AP2S1 mutations." (PMID 38130397, 2023). "The genetic testing for calcium sensing receptor is beneficial to distinguish asymptomatic primary hyperparathyroidism from FHH." (PMID 35733207, 2022). "Characteristics of studies included in the meta-analysis for the relationship between CaSR rs1801725 gene polymorphism and PTH level in primary hyperparathyroidism patients." (PMID 29794776, 2018). "Can CaSR expression be effectively upregulated in hypercalcemic conditions such as primary hyperparathyroidism or FHH to restore physiological control of plasma calcium levels and Ca2+o-dependent suppression of PTH secretion?" (PMID 28018229, 2016). "We investigated the consequence of CaSR knock down in a mouse model in which exon-5 of the CaSR gene is globally ablated on a PTH-null background to prevent the development of catastrophic primary hyperparathyroidism." (PMID 25701758, 2015). "In recent studies, CaSR expression in parathyroid glands (PTGs) was shown to decrease in cases of primary hyperparathyroidism, as measured by several different techniques including immunohistochemistry." (PMID 25254042, 2014). "CaSR agonists, such as cinacalcet, are indicated in secondary and primary hyperparathyroidism." (PMID 28122587, 2017). "The human CASR gene is located on chromosome 3q21.1, and loss-of-function CaSR mutations have been reported in the hypercalcemic disorders of familial benign (hypocalciuric) hypercalcemia (FBHH), neonatal severe primary hyperparathyroidism (NSHPT) and familial isolated hyperparathyroidism (FIHP)." (PMID 18446382, 2009). "The presence of hyperplastic or adenomatous parathyroid cells, patchy fibrosis areas, oxyphilic cell clusters and haematoma areas could be responsible for the reduction in CasR expression in primary hyperparathyroidism and consequently for the lower brightness of the fluorescence signals." (PMID 39682204, 2024).